NPC1L1 (NPC1 like intracellular cholesterol transporter 1)
Description:
Plays a major role in cholesterol homeostasis. Critical for the uptake of cholesterol across the plasma membrane of the intestinal enterocyte. Involved in plant sterol absorption, it transports sitosterol, although at lower rates than cholesterol (By similarity). Is the direct molecular target of ezetimibe, a drug that inhibits cholesterol absorption and is approved for the treatment of hypercholesterolemia. May have a function in the transport of multiple lipids and their homeostasis, thereby influencing lipid metabolism regulation. May be involved in caveolin trafficking from the plasma membrane (By similarity). In addition, acts as a negative regulator of NPC2 and down-regulates its expression and secretion by inhibiting its maturation and accelerating its degradation.
Synonyms: SLC65A2; LDLCQ7; NPC11L1
Tractability: Small molecule: an approved drug acts on it; a structure with a bound ligand is known; a high-quality ligand is known; it belongs to a druggable protein family. Antibody: UniProt places it where antibodies can reach, with high confidence; its Gene Ontology location is reachable by antibodies, with high confidence; UniProt predicts a signal peptide or a membrane-spanning region. PROTAC: its protein half-life has been measured; a small molecule that binds it is known.
Target class: Other membrane protein
Gene: Protein-coding gene on chromosome 7 (44,512,535 to 44,541,330, reverse strand). Ensembl gene ENSG00000015520.
Subcellular location: Apical cell membrane; Cell membrane; Cytoplasmic vesicle membrane
Pathways (Reactome):
Digestion and absorption: Intestinal lipid absorption
Gene Ontology:
Molecular function: cholesterol binding; myosin V binding; protein binding; protein homodimerization activity; small GTPase binding; vitamin E binding
Biological process: cellular response to sterol depletion; cholesterol biosynthetic process; cholesterol transport; intestinal cholesterol absorption; lipoprotein metabolic process; vitamin E metabolic process; vitamin transport; cholesterol homeostasis; sterol transport
Cellular component: plasma membrane; apical plasma membrane; cytoplasmic vesicle membrane
Genetic constraint (gnomAD): Loss-of-function variants: 98 observed, 121.34 expected, observed/expected ratio (o/e) 0.81, 90% interval 0.69 to 0.95. The upper end of that interval is the gene's LOEUF score, 0.95, which puts it in group 4 of 6, group 1 being the genes least tolerant of losing a copy. Missense variants: 1,540 observed, 1,778.4 expected, observed/expected ratio (o/e) 0.87, 90% interval 0.83 to 0.9. Synonymous variants: 729 observed, 760.82 expected, observed/expected ratio (o/e) 0.96, 90% interval 0.9 to 1.02.
Homologues: Orthologues: chimpanzee NPC1L1 (99% identical), macaque NPC1L1 (95% identical), pig NPC1L1 (82% identical), dog NPC1L1 (81% identical), rabbit NPC1L1 (80% identical), rat Npc1l1 (78% identical), mouse Npc1l1 (77% identical), tropical clawed frog npc1l1 (57% identical), zebrafish NPC1L1 (42% identical), Drosophila melanogaster Ptr (14% identical), Caenorhabditis elegans ptr-17 (13% identical). Paralogues in human: NPC1 (38% identical), PTCH1 (20% identical), PTCH2 (18% identical), PTCHD3 (15% identical), DISP3 (14% identical), DISP2 (14% identical), DISP1 (14% identical), PTCHD1 (12% identical), PTCHD4 (12% identical), SCAP (10% identical).
Diseases named in the same sentence as NPC1L1 in open-access papers:
NPC1L1 is named in the same sentence as 124 diseases in open-access papers, as found by Europe PMC text mining. Sharing a sentence is not in itself a finding about the gene and the disease. The quoted sentences say what the papers report.
atherosclerosis (20 papers, 2018 to 2026). A disease characterized by the build-up of fatty material and calcium deposition in the arterial wall resulting in partial or complete occlusion of the arterial lumen. "Given the strong connection of Sortilin to cardiovascular disease, we sought to assess if under atherosclerosis-related conditions, Sort1 deficiency alters adipose tissue function, weight gain, and NPC1L1-mediated cholesterol absorption in male and female mice." (PMID 29899496, 2018). "Mechanically, increased 3‐MH facilitated atherosclerosis progression through NPC1L1‐mediated intestinal cholesterol absorption in a HNF1A‐dependent manner." (PMID 39949981, 2025). "Patients on long-term treatment with phytosterols must be checked for their genetic polymorphisms in NPC1L1 and ABCG5/G8 transport proteins in order to avoid phytosterol aggregation and induction of atherosclerosis." (PMID 40004982, 2025). "Long‐term adherence to a diet rich in chicken protein accelerated atherosclerosis through an enhanced microbial production of 3‐Methyl‐L‐histidine, which in turn facilitated NPC1L1‐mediated intestinal cholesterol absorption." (PMID 39949981, 2025). "Fucoidan has also been found to reduce NPC1L1 expression, inhibit cholesterol uptake in the intestine, and prevent hyperlipidemia-induced atherosclerosis in apoE−/− mice." (PMID 38132943, 2023). "Meanwhile, drugs targeting NPC1L1 on the small intestine, such as ezetimibe, have been widely used in the treatment of atherosclerosis." (PMID 36451858, 2022). "In a study investigating the potential of bexarotene in atherosclerosis, the mRNA levels of both NPC1L1 and ABCA1 were found to be reduced in the duodenum and jejunum of bexarotene-treated mice, supporting our findings." (PMID 32308567, 2020). "Thus, at present, there are insufficient data to support the role of the p.(Val177Ile)/p.(His221Tyr)/p.(Ala271Phe) haplotype of the NPC1L1 gene in the development of dyslipidemia and atherosclerosis." (PMID 42253452, 2026). "However, Ezetimibe, which directly targets NPC1L1, has been widely used in the treatment of hypercholesterolemia and atherosclerosis by reducing intestinal cholesterol absorption." (PMID 40832101, 2025). "We speculated that the variation of SNP may result in the activation of NPC1L1 gene function, which leads to an increase in the level of LDL-C, and leads to the progression of atherosclerosis, causing premature coronary heart disease." (PMID 34926596, 2021). "To our knowledge, we first reported the relationship between lipid regulatory genes NPC1L1 and HMGCR and CAC, revealing that variations on lipid regulatory genes play a crucial role in the occurrence and progression of atherosclerosis." (PMID 38233830, 2024). "Clinical therapeutic strategies for atherosclerosis are mainly focused on maintaining a lower level of blood LDL by statins, NPC1L1 and PCSK9 inhibitors." (PMID 37963874, 2023). "We speculated that the variation of this SNP might activate NPC1L1 gene function, increasing the level of LDL-C, and then leads to the progression of atherosclerosis and CAC." (PMID 38233830, 2024). "Niemann-Pick C1-like 1 (NPC1L1) and 3-hydroxy-3-methylglutaryl-coenzyme A reductase (HMGCR) are the therapeutic targets of ezetimibe and statins, respectively, which are important for the progression of atherosclerosis." (PMID 38233830, 2024).
Hypercholesterolemia (19 papers, 2005 to 2026). An increased concentration of cholesterol in the blood. "Among the options to successfully lower atherogenic blood lipids are therapeutics against drug targets that when mutated cause familial hypercholesterolemia (FH), such as NPC1L1, the target of ezetimibe, or PCSK99." (PMID 34741066, 2021). "Recent studies have shown the increase in NPC1L1 expression in hypercholesterolemia associated with diseases such as diabetes mellitus." (PMID 28057006, 2017). "Suppression of NPC1L1-mediated dietary and biliary cholesterol absorption is predicted to be one of the most effective ways to reduce the risk of hypercholesterolemia." (PMID 25551765, 2014). "Moreover, NPC1L1 inhibition or deficiency was shown to protect against diet-induced hypercholesterolemia and hepatic steatosis." (PMID 28057006, 2017). "It was demonstrated that ezetimibe, a small molecule compound used in the treatment of hypercholesterolemia, inhibits cholesterol absorption by binding to the second extracellular loop region of NPC1L1 to block the formation of endocytic vesicles." (PMID 39872735, 2023). "Niemann–Pick C1 Like-1 (NPC1L1) has been identified as a potential therapeutic target for hypercholesterolemia." (PMID 36234807, 2022). "By specifically blocking the NPC1L1 protein at the jejunal brush barrier, NPC1L1 inhibitors prevent intestinal cholesterol absorption and offer a vital adjunctive method for treating hypercholesterolemia." (PMID 36234807, 2022). "NPC1L1 knockout (L1-KO) mice exhibit greatly reduced intestinal cholesterol absorption and are resistant to high cholesterol-containing diet-induced hypercholesterolemia." (PMID 34943976, 2021). "Niemann–Pick C1-like 1 (NPC1L1) mediates intestinal uptake of dietary and biliary cholesterol and is the target of ezetimibe, a cholesterol absorption inhibitor used to treat hypercholesterolemia." (PMID 34943976, 2021). "NPC1L1 knockout mice exhibited an 70% reduction in cholesterol absorption and were resistant to diet-induced hypercholesterolemia." (PMID 28057006, 2017). "Niemann–Pick C1-Like 1 (NPC1L1) mediates cholesterol absorption, and ezetimibe is a potent NPC1L1 inhibitor applicable for medication of hypercholesterolemia." (PMID 24859282, 2014). "Therefore, the reduction in NPC1L1 in BE-treated cells demonstrates the potential of BE in the prevention of hypercholesterolemia." (PMID 34829135, 2021). "Clinically, Eze, a NPC1L1 inhibitor, is mainly used as a treatment for hypercholesterolemia; however, in addition to its lipid-lowering activity, several studies have reported that Eze may attenuate ischemic-related oxidative stress and inflammation." (PMID 31998437, 2020). "This review also explores the effect of other polyphenols on NPC1L1 and hypercholesterolemia." (PMID 31590417, 2019). "These accumulating data suggest that the inhibition of NPC1L1-dependent cholesterol uptake by ezetimibe may be a suitable therapeutic target for treatment of not only hypercholesterolemia but also broader aspects of metabolic disorders in patients with type 2 diabetes and/or metabolic syndrome." (PMID 19821987, 2009). "Furthermore, PTL reduced the expression of NPC1L1 in HepG2 cells in a concentration-dependent manner, which suggests that PTL functions as a potential NPC1L1 inhibitor with therapeutic potential for hypercholesterolemia." (PMID 36234807, 2022).
dyslipidemia (17 papers, 2009 to 2026). "For complex disorders, variants in genes with clear biological and clinical importance, such as LDLRAP1, SCARB1, and NPC1L1 have been identified, corresponding to approximately 25% - 30% of the genetic variance for various dyslipidemia traits." (PMID 38938445, 2024). "We tested SNPs in two genes (HMGCR and NPC1L1) related to dyslipidemia in PTVD patients treated with moderate-intensity statins, and investigated the association between their SNPs and RCR (LDL-C > 1.8 mmol/L)." (PMID 37355634, 2023). "NPC1L1, a key protein affecting cholesterol uptake, refers to a therapeutic target of dyslipidemia, while ezetimibe serves as a selective inhibitor of NPC1L1." (PMID 35510250, 2022). "NPC1L1 is essential for the intestinal absorption of cholesterol, and is a target of ezetimibe, a drug used to treat dyslipidemia recalcitrant to statin treatment." (PMID 34511128, 2021). "Niemann-Pick C1-Like 1 (NPC1L1) is a cholesterol importer and target of ezetimibe, a cholesterol absorption inhibitor used clinically for dyslipidemia." (PMID 32872588, 2020). "We also demonstrated a new potency of ezetimibe, an NPC1L1‐selective inhibitor clinically used against dyslipidemia, as a preventive and curative drug for steatosis, which will be of importance in terms of drug repositioning." (PMID 32123832, 2019). "Some polyphenols, particularly luteolin, have been reported as NPC1L1-mediated anti-dyslipidemia constituents." (PMID 31590417, 2019). "Importantly, NPC1L1 is a target of ezetimibe, a drug that is used to treat dyslipidemia that cannot be managed using statin treatment." (PMID 34511128, 2021). "NPC1L1 functions as a cholesterol importer to mediate intestinal cholesterol absorption, and is reported to be a target molecule of ezetimibe, a cholesterol absorption inhibitor used clinically for dyslipidemia." (PMID 32872588, 2020). "Additionally, the LDL-lowering effect of ezetimibe was significantly greater in DM, suggesting the potentially beneficial role of ezetimibe as a NPC1L1 inhibitor in the treatment of DM with dyslipidemia and vascular dysfunction." (PMID 25903215, 2015). "In addition, the GLXB herb pair exerted therapeutic effects on dyslipidemia in ApoE-/- mice by increasing the level of butyric acid, a metabolite of the gut microbiota, decreasing the expression of NPC1L1, MTP, ACAT2, and ApoB48 proteins, and inhibiting the intestinal absorption of cholesterol." (PMID 41466480, 2025). "Thus, myriocin induced improvement in dyslipidemia and hepatic steatosis in our study may also be related to changes in NPC1L1, CD36 and FATP4 expression and alterations in lipid raft composition that reduce intestinal fatty acid and cholesterol uptake." (PMID 25993337, 2015). "This study suggests that laminarin significantly improves dyslipidemia in HFD-fed mice, likely by reducing cholesterol uptake through a mechanism that involves the downregulation of NPC1L1 expression." (PMID 38132943, 2023). "NPC1L1 plays a crucial role in cholesterol absorption in the intestines and is targeted by ezetimibe, a medication commonly prescribed for managing dyslipidemia that does not respond well to statins." (PMID 39598242, 2024). "Apigenin could attenuate dyslipidemia and subsequent atherosclerotic conditions through down-regulating SREBP-1c, SREBP-2, FAS, stearyl-CoA desaturase 1, HMG-CoA reductase, TLR-4, Npc1l1, MyD88, p-IκB-α, and NF-κB p65 which are involved in inflammation and atherosclerotic plaques formation." (PMID 38629096, 2024). "In addition to differences in NPC1L1 protein expression, a disturbance in the ATP binding cassette (ABC) proteins G5 and G8, which regulate cholesterol homeostasis, may play a role in the dyslipidemia of diabetic patients." (PMID 20492655, 2010).
dyslipidemia (continued). "Interestingly, ezetimibe, a pharmacological inhibitor of the NPC1L1 cholesterol transporter, has shown significant benefit in both animal models and patients with LALD, consistent with noncanonical LDL pathways modifying the LALD dyslipidemia phenotype." (PMID 32093730, 2020).
coronary heart disease (16 papers, 2015 to 2025). "SNP rs217406 of the NPC1L1 gene showed significant association with an increased risk of coronary artery disease exclusively in smokers (p = 0.01)." (PMID 35203469, 2022). "Our study showed that the rs4720470 of NPC1L1 was associated with the risk of premature coronary heart disease and TVD, which was 1.74 times higher than that of the control group." (PMID 34926596, 2021). "A recent study utilizes naturally occurring genetic variation within the NPC1-like 1 gene (NPC1L1) to demonstrate the potential for pharmacologic inhibition of the protein to reduce the risk of coronary heart disease." (PMID 25628760, 2015). "Recently, it has been reported that inactivating mutations in the NPC1L1 gene provided significant protection against coronary heart disease." (PMID 25903215, 2015). "The authors concluded that the genetic inhibition of NPC1L1 may also lower the risk of coronary heart disease by reducing the absorption of plant sterols." (PMID 34468867, 2021). "Furthermore, lifelong genetic inhibition of NPC1L1 was found to be associated with reduced risk of coronary heart disease, suggesting an essential role of NPC1L1 on protection from CV disease." (PMID 30093717, 2018). "In recent years, the gene polymorphism of NPC1L1 and HMGCR has attracted more and more attention in coronary heart disease (CHD)." (PMID 34926596, 2021). "Naturally occurring mutations that disrupt NPC1L1 functions were found to be associated with reduced plasma LDL cholesterol levels and a reduced risk of coronary heart disease." (PMID 34349727, 2021). "IVW-MR association between LDL cholesterol mediated by gene HMGCR, PCSK9, NPC1L1 or APOB and coronary heart disease." (PMID 37528862, 2023). "Likewise, there was no clear evidence of heterogeneity (all p > 0.05) or pleiotropy (all p values for intercept > 0.05) regarding HMGCR, NPC1L1 and PCSK9 in erectile dysfunction and positive control coronary heart disease." (PMID 38097781, 2023).
Hepatic steatosis (13 papers, 2010 to 2025). Steatosis is a term used to denote lipid accumulation within hepatocytes. "Recent findings have shown that NPC1L1 deficiency or NPC1L1 inhibition reduces blood cholesterol and prevents hepatic steatosis and diet-induced obesity." (PMID 38778308, 2024). "Inhibition of NPC1L1 by Ezetimibe is associated with an improvement in hepatic steatosis." (PMID 22007304, 2012). "For instance, studies have demonstrated that the genetic deletion or pharmacological inhibition of NPC1L1 reduces hepatic cholesterol content and ameliorates liver steatosis in high-fat diet (HFD)-fed NAFLD mice." (PMID 40141435, 2025). "Ultimately, cryptotanshinone (CTS) was identified as a novel NPC1L1 inhibitor and significantly decreased hepatic steatosis in HFD-fed mice." (PMID 40141435, 2025). "Both genetic and pharmacological inactivation of Npc1l1 counteract the development of hepatic steatosis in mice fed high-fat diets, by decreasing the amount of hepatic cholesterol." (PMID 37886435, 2023). "Animal knockout models of NPC1L1 or treatment with an inhibitor of NPC1L1-dependent cholesterol transport provides resistance against hepatic steatosis." (PMID 20222991, 2010). "Ultimately, CTS, the liposoluble compound in Danshen, was identified as a novel NPC1L1 inhibitor and significantly alleviated hepatic steatosis in HFD-fed NAFLD mice, suggesting that CTS may exert its protective effect against NAFLD by inhibiting NPC1L1." (PMID 40141435, 2025). "In our study, CTS, the novel NPC1L1 inhibitor, significantly alleviated hepatic steatosis in HFD-fed mice, indicating that the therapeutic effect of CTS against NAFLD may be regulated by inhibiting NPC1L1-mediated intestinal cholesterol absorption." (PMID 40141435, 2025). "The target protein of ezetimibe, NPC1-L1, known to be present in the intestine, was recently shown to be present in hepatocyte and Kupffer cells, affecting bile cholesterol reabsorption, which is expected to have a pleiotropic effect on hepatic steatosis." (PMID 35307033, 2022). "In addition, hepatic NPC1-L1 induces hepatic steatosis by participating in cholesterol reabsorption from bile to the liver, which can be inhibited by ezetimibe." (PMID 35307033, 2022). "Also in animal models, inactivation of NPC1L1, a critical mediator of cholesterol absorption, shows protective effects against diet-induced hypercholesterolemia and fatty liver, and ezetimibe treatment improves liver steatosis and insulin resistance in obese rat models." (PMID 23197979, 2012).